NR4A2 (nuclear receptor subfamily 4 group A member 2)
Diseases named in the same sentence as NR4A2 in open-access papers (continued):
Sharing a sentence is not in itself a finding about the gene and the disease.
NR4A2 also shares sentences with these, for which no sentence is quoted: Parkinson’s (24 papers); hearing loss (11); deafness (7); synucleinopathies (6); attention deficit-hyperactivity disorder (5); Cerebral ischemia (5); psoriasis (5); Stroke (5); tauopathies (5); squamous cell carcinoma (4); amyotrophic lateral sclerosis (3); hepatocellular carcinoma (3); type 2 diabetes (3); adrenal hypoplasia (2); bladder tumor (2); dilated cardiomyopathy (2); Hearing impairment (2); Hyperinsulinemia (2); intracerebral hemorrhage (2); lactic acidosis (2); lymph node metastasis (2); neurotoxicity (2); pancreatic ductal adenocarcinoma (2); psoriatic arthritis (2); Rolandic epilepsy (2); skin cancer (2); ZIKV infection (2); 22q11.2 deletion syndrome (1); acute kidney injury (1); acute myeloid leukemia (1).
A further 92 diseases each share a sentence with NR4A2 in 1 paper.